Y_RNA (Y RNA )
Gene: Miscellaneous RNA gene on chromosome 7 (4,811,188 to 4,811,289, reverse strand). Ensembl gene ENSG00000206895.
Homologues: Orthologues: chimpanzee Y_RNA (99% identical), macaque Y_RNA (96% identical). Paralogues in human: RNY3 (89% identical), Y_RNA (89% identical), Y_RNA (88% identical), RNY3P14 (87% identical), Y_RNA (87% identical), RNY3P1 (86% identical), Y_RNA (86% identical), RNY3P5 (85% identical), Y_RNA (85% identical), Y_RNA (84% identical), Y_RNA (83% identical), RNY3P11 (82% identical), and 95 more.